CNIH2 (cornichon family AMPA receptor auxiliary protein 2)
Description:
Regulates the trafficking and gating properties of AMPA-selective glutamate receptors (AMPARs). Promotes their targeting to the cell membrane and synapses and modulates their gating properties by regulating their rates of activation, deactivation and desensitization. Blocks CACNG8-mediated resensitization of AMPA receptors.
Synonyms: CNIH-2; CNIL; MGC50896
Tractability: Small molecule: a structure with a bound ligand is known. Antibody: UniProt places it where antibodies can reach, with medium confidence; UniProt predicts a signal peptide or a membrane-spanning region; its Gene Ontology location is reachable by antibodies, with medium confidence.
Gene: Protein-coding gene on chromosome 11 (66,278,175 to 66,285,301, forward strand). Ensembl gene ENSG00000174871.
Subcellular location: Endoplasmic reticulum membrane; Postsynaptic cell membrane; Cell projection, dendrite; Cell projection, dendritic spine; Postsynaptic density
Pathways (Reactome):
Vesicle-mediated transport: COPII-mediated vesicle transport; Cargo concentration in the ER
Gene Ontology:
Molecular function: protein binding; signaling receptor binding
Biological process: regulation of AMPA receptor activity; synaptic transmission, glutamatergic; vesicle-mediated transport
Cellular component: AMPA glutamate receptor complex; dendrite; dendritic shaft; dendritic spine; endoplasmic reticulum membrane; endoplasmic reticulum-Golgi intermediate compartment membrane; ER to Golgi transport vesicle membrane; postsynaptic density; postsynaptic membrane; synapse
Genetic constraint (gnomAD): Loss-of-function variants: 7 observed, 20.22 expected, observed/expected ratio (o/e) 0.35, 90% interval 0.2 to 0.65. The upper end of that interval is the gene's LOEUF score, 0.65, which puts it in group 2 of 6, group 1 being the genes least tolerant of losing a copy. Missense variants: 98 observed, 186.7 expected, observed/expected ratio (o/e) 0.52, 90% interval 0.44 to 0.62. Synonymous variants: 73 observed, 74.11 expected, observed/expected ratio (o/e) 0.99, 90% interval 0.81 to 1.2.
Homologues: Orthologues: chimpanzee CNIH2 (100% identical), dog CNIH2 (100% identical), guinea pig CNIH2 (100% identical), macaque CNIH2 (100% identical), mouse Cnih2 (100% identical), zebrafish cnih2 (90% identical), tropical clawed frog cnih2 (88% identical), rat Cnih2 (85% identical), Drosophila melanogaster cni (47% identical), Caenorhabditis elegans cni-1 (44% identical). Paralogues in human: CNIH3 (81% identical), CNIH1 (65% identical), CNIH4 (27% identical), PPCS (21% identical).
Diseases named in the same sentence as CNIH2 in open-access papers:
CNIH2 is named in the same sentence as 13 diseases in open-access papers, as found by Europe PMC text mining. Sharing a sentence is not in itself a finding about the gene and the disease. The quoted sentences say what the papers report.
gout (7 papers, 2017 to 2023). A condition characterized by painful swelling of the joints, which is caused by deposition of urate crystals. "Rs4073582 of CNIH-2 gene was associated with gout in three independent cohorts including two Japanese male and a Han Chinese male." (PMID 30123371, 2018). "Some of the previously reported gout associated loci (except ALDH16A1), including ABCG2, SLC2A9, GCKR, ALDH2 and CNIH2, were replicated." (PMID 28642574, 2017). "And 11 of the significant variants were from the gout associated loci (GCKR, SLC2A9, ABCG2, CNIH2, MYL2-CUX2 (ALDH2) and BCAS3)." (PMID 28642574, 2017). "Especially, by performing a GWAS of clinically-ascertained gout, our Japanese report identified five gout loci including MYL2-CUX2 and cornichon family AMPA receptor auxiliary protein 2 (CNIH-2)." (PMID 29879923, 2018).
schizophrenia (2 papers, 2021 to 2025). A major psychotic disorder characterized by abnormalities in the perception or expression of reality. "In particular, genes associated with male-biased neurological diseases (e.g., NEUROD6 for autism, CNIH2 for schizophrenia) were differentially expressed between DHT- and nonresponded neurons but not between DHT and mock-treated neurons." (PMID 39622637, 2025).
breast carcinoma (1 paper, 2023). "Therefore, CNIH2 may play a role in breast cancer progression through interaction with AMPA." (PMID 36911413, 2023).
migraine (1 paper, 2023). "Furthermore, variations in CNIH-2, which modulates glutamate receptor function in neurons and glial cells, might indirectly influence migraine susceptibility as glutamate is significantly involved in migraine pathophysiology." (PMID 38202145, 2023).
myopathy (1 paper, 2022). A disease of the muscle in which the muscle fibers do not function properly. "Forty-six candidate genes are prioritized by multiple approaches (42 for LST and 6 for MVPA; 2 overlap) and point to endocytosis (CNIH2, RAB1B, KLC2, PACS1, REPS1, DNM3, EXOC4), locomotion (CADM2, KLC2) and myopathy (MLF2, HERC1, KLC2, SIL1) as relevant pathways." (PMID 36071172, 2022).
CNIH2 also shares sentences with these, for which no sentence is quoted: Alzheimer disease (1 paper); autism (1); autism spectrum disorder (1); cancer (1); diabetes mellitus (1); neurological diseases (1); prostate carcinoma (1); tumor (1).